PIM2 (Pim-2 proto-oncogene, serine/threonine kinase)
Diseases named in the same sentence as PIM2 in open-access papers (continued):
Sharing a sentence is not in itself a finding about the gene and the disease.
tumor (51 papers, 2009 to 2026). "Pim2 deficiency enhanced cytokine production and metabolic activities in tumor-infiltrating CD8 T cells." (PMID 41592107, 2026). "Inhibition of Pim-2 decreased the proliferation of MM tumor cells and increased their susceptibility to apoptosis." (PMID 36612063, 2022). "Clinically, the up-regulation of PIM2 has been significantly associated with vascular invasion, recurrence, and tumor node metastasis staging." (PMID 33854618, 2021). "Previous studies on Pim2 have focused primarily on its roles in promoting tumor cell survival and preventing apoptosis." (PMID 40000906, 2025). "Among the three PIM kinases, PIM1 exhibited a positive regulation on the memory fitness of T cells, while PIM2 negatively modulated their anti-tumor responses." (PMID 41199316, 2025). "Considering the tumor heterogeneity of the two clusters, we identified six prognostic genes (PIM2, PET117, SMARCA5, TAF9, ABCB10, MKP1) among the m6A-hypoxia genes and developed a scoring system to evaluate m6A modification patterns and hypoxia status." (PMID 36105819, 2022). "Meanwhile, Mono-FCGR3A both in high and low tumor infiltration group expressed high level of PIM2/PIM3 compared to HDs." (PMID 36532059, 2022). "Our data suggest that reduced Pim-2 expression inhibits the energy metabolism process in MM, thereby inhibiting tumor progression." (PMID 36612063, 2022). "Further, PKM2 translocates to the nucleus after Thr-454 phosphorylation by PIM2, which decreases mitochondrion function and enhances the pentose-phosphate pathway, and ultimately enhances both cell proliferation and tumor growth." (PMID 33854618, 2021). "Here, we summarize the signaling pathways involved in PIM2 kinase regulation and PIM2 mechanisms in various neoplastic diseases." (PMID 33854618, 2021). "We extensively looked for factors responsible for MM tumor growth and survival in bone lesions and found the serine/threonine kinase PIM2 as a critical mediator in MM cell growth and survival." (PMID 34503251, 2021). "PIM2 promotes tumor progression in many ways; however, its mechanism in glycolysis and tumor resistance is poorly understood." (PMID 33931981, 2021). "PIM2, a downstream target of miR-24-3p, has already been shown to exert tumor-promoting effects in different carcinomas." (PMID 34511042, 2021). "We next wished to examine the relative sensitivity to Pim2 inhibition of human tumor-derived B cell lines with varying levels of TRAF3 protein." (PMID 31501481, 2019). "Downstream genes activated by STAT3 have been associated with tumor proliferation and survival, including PIM1/PIM2, MYC, BIRC5 and BCL2L134–39." (PMID 30741931, 2019). "Emerging evidence has shown that the PIM serine/threonine kinase family, including PIM1, PIM2 and PIM3, is associated with tumour progression towards metastasis." (PMID 29472550, 2018). "PIM2 lacks a regulatory domain and thus is constitutively activated, a trait which is used in the design of tumor drugs." (PMID 29570932, 2018). "These analyses showed a clear list of genes associated to antigen presentation that significantly correlated with PIM1 and PIM2 expression in all tumor types." (PMID 28938604, 2017). "PIM2 promotes tumor survival mainly through phosphorylation of the pro-apoptotic BH3-only protein BAD, as well as through regulation of MYC activity, and Cap-dependent protein translation." (PMID 28561737, 2017). "Furthermore, genes associated with proliferation and survival, including CD69, EGR1 (early growth response protein 1), and PIM2 (proviral integrations of moloney virus 2), were increased, suggesting a potential role in tumor progression." (PMID 40809351, 2025). "Interestingly, inhibiting PIM kinases, including PIM2, significantly enhanced the antitumor efficacy of T cells in tumor-bearing mice undergoing Adoptive T cell therapy." (PMID 39132169, 2024). "Pim-2 is known to play an important role in aerobic glycolysis and tumor development." (PMID 36612063, 2022).
tumor (continued). "We found that CD8-GNLY effector T cells in high tumor infiltration group displayed increasing level of the serine/threonine kinase PIM family (PIM2 and PIM3), NR4A2/3, KLF4/6, BCL2, GPR183 and COTL1 compared to the ones from HD and low tumor infiltration group." (PMID 36532059, 2022). "PIM2 was targeted by miR-24-3p and showed increased levels in tumor tissues and cells." (PMID 34511042, 2021). "Moreover, a synergistic function of Pim2 and C-Myc was reported to have an antiapoptotic effect; Pim2 is recognized as a partner gene of C-Myc during the induction and development of tumor." (PMID 33564319, 2021). "In addition, PIM2 plays an important role in tumor progression by phosphorylating its downstream substrate proteins." (PMID 32754266, 2020). "PIM-2 also negatively regulates anti-tumor response by restraining T cell responses." (PMID 32062612, 2020). "Although TRAF3 levels inversely correlated with Pim2 expression in tumor-derived B cells as well as their primary cell counterparts, low expression of TRAF3 increased susceptibility to Pim inhibition in human malignant B cells, in contrast to resistance to Pim inhibitors in primary B cells." (PMID 31501481, 2019). "However, in these cancer types, PIM1 and PIM2 can be overexpressed in the same tumor, which suggests that there is only a partial redundancy among them." (PMID 28938604, 2017). "The PIM2 structure and inhibitor data presented here provide further direction to develop well-tolerated drug molecules that stop growth factor independence, limit drug resistance and induce tumour apoptosis." (PMID 19841674, 2009). "PIM2 as a kinase could phosphorylate a series of proteins that are essential for tumor progression." (PMID 29570932, 2018). "An in vitro co‐culture of MM and NK cells assessed the effects of SMI‐16a (PIM‐2 inhibitor) and ABT888 (PARP1 inhibitor) on tumor proliferation and apoptosis, focusing on DNA damage, MICA expression, and NK cell functionality." (PMID 40557764, 2025). "Seven GRPGs (PIM2, PGK1, ADPGK, YWHAZ, PTK2, PGAM1, and VDAC1) were significantly upregulated in the TCGA-BRCA tumor tissues." (PMID 40046063, 2025). "Phosphorylation of HK2 at Thr473 by PIM2 enhances HK2 stability and activity and promotes glycolysis, tumor growth, and drug resistance to paclitaxel." (PMID 37143582, 2023). "While targeted inhibition of PIM2 and HSF1 resulted in decreased tumor size in each case, combined treatment had a synergistic effect and arrested tumor growth entirely in murine xenografts." (PMID 35311075, 2022). "PIM2 and other PIM kinases are rational targets of pan anti-cancer therapeutics as they involve in tumorigenesis and tumor progression of many cancers." (PMID 34770845, 2021). "In this study, we found that regulated by TNFα, Pim-2 proto-oncogene, serine/threonine kinase (PIM2) was highly expressed in HCC and correlated with poor prognosis (P = 0.007) as well as tumor recurrence (P = 0.014)." (PMID 32641749, 2020). "Consistently, PIM2 and FBP1 Ser144 phosphorylation were expressed at higher levels in the tumor samples than in the normal control samples." (PMID 32754266, 2020). "We fully characterized the tumor responses to these genetic alterations in both PIM1 and PIM2 models, corroborating their role as oncogenes by inducing a hyperproliferation state in tissues of the male reproductive system." (PMID 27901106, 2016). "A recent study in a cancer cell line indicated that CHES1/FOXN3 decreases cell proliferation by repressing PIM2 and protein biosynthesis, suggesting that FOXN3 is a potential tumor suppressor." (PMID 27281616, 2016). "This drug exerts good efficacy in tumor suppression and osteoclast genesis based on its excellent inhibition of Pim‐1/Pim‐2, and it was a safe and reliable drug, as no significant toxic side effects were found in bone marrow and liver." (PMID 41323479, 2025).
tumor (continued). "Our study demonstrates that PIM2 mediates PFKFB3 phosphorylation thus regulates glycolysis and paclitaxel resistance to promote tumor progression in BC and provides preclinical evidence for targeting PFKFB3 as a new strategy in BC treatment to battle paclitaxel resistance." (PMID 33931981, 2021). "Upregulation of PIM2 (defined as >2-fold increase in tumor tissues compared with paired nontumor tissues) was detected in 73/134 (54.5%) of HCCs." (PMID 32641749, 2020). "While CAPZA1, CAPZA2 and CAPZB, but not CAPZA3 levels correlated well with PIM1 levels in all tumor tissues, similar correlations were also observed for PIM2 and PIM3 in the samples with high Gleason scores." (PMID 32771000, 2020). "In the present study, expression of PIM2 was compared between tumor and corresponding adjacent nontumor tissues by qRT-PCR in 134 primary HCCs." (PMID 32641749, 2020). "As a transcription regulator, FOXN3 has been reported to inhibit the expression of some tumour oncogenes, such as PIM2 and E2F5.9, 34 However, the negative correlation between FOXN3 and PIM2 or E2F5 was not validated in this study." (PMID 32078244, 2020). "PIM2 is a typical oncogene in many cancers, but TTP is reported as a tumor suppressor." (PMID 29570932, 2018). "Tumor samples were collected following 3 days of treatment and PIM expression levels were not consistently changed across treatment groups; however, the presence of PLX4720 correlated with higher PIM2 levels." (PMID 27448973, 2016). "It suggests that the regulatory feedback loop between PIM2 and HIF-1α may facilitate tumor cells to adapt to hypoxia." (PMID 24505470, 2014). "The average ΔCt value of PIM2 in HCC tumor tissues was significantly lower than that in nontumor tissues (P < 0.001, paired Student t test), indicating that the relative expression level of PIM2 was dramatically higher in tumor tissues." (PMID 32641749, 2020). "Although we expect that there are multiple gene alterations in tumor cells that could impact Pim2 expression, our results indicate that TRAF3 likely serves as an important regulator to restrain Pim2 expression at both the mRNA and protein levels in normal and malignant B cells." (PMID 31501481, 2019). "The lack of Pim2 and Pim3 reduced tumor-induced bone invasion by 70%, and this reduction is comparable to the reduction of tumor-induced bone invasion in the absence of all three isoforms, although the absence of all three isoforms is necessary to achieve the maximum effect." (PMID 24860787, 2014). "Our results revealed the tumor-induced endothelial JAK-STAT-PIM-BCL3 axis both in vitro and in vivo, with upregulation of also Pim1 in rCap, albeit less than Pim3, whereas Pim2 was not expressed in the lung ECs." (PMID 39627185, 2024). "The Pim-2 (PIM2) is a novel oncogene and its protein has a profound inhibitory effect on the apoptosis of tumor cells without cell specificity." (PMID 23023193, 2012).
cancer (45 papers, 2006 to 2026). A tumor composed of atypical neoplastic, often pleomorphic cells that invade other tissues. "Several studies demonstrated that PIM2 dysregulation was associated with several cancers, e.g., lymphoma, leukemia, multiple myeloma, prostate cancer, hepatocellular carcinoma." (PMID 34770845, 2021). "Additionally, PocketMiner predicts a cryptic pocket in PIM2, a kinase implicated in multiple cancers." (PMID 36859488, 2023). "However, the underling mechanisms for the regulation of cancer by PIM2 are not yet fully understood." (PMID 33854618, 2021). "Collectively, PIM2 represents a promising target for improving cancer immunotherapy through enhancing effector differentiation and persistence of CD8 T cells." (PMID 41592107, 2026). "PIM2 is undergoing investigation as a therapeutic target in MM (Phase I trials) and three other cancers." (PMID 35882937, 2022). "We also discuss the current status and future perspectives for the development of PIM2 kinase inhibitors to combat human cancer, and PIM2 will become a therapeutic target in cancers in the future." (PMID 33854618, 2021). "Several chemical inhibitors targeting PIMs/PIM2 or their downstream signaling molecules have been developed for treatment of a variety of cancers." (PMID 34770845, 2021). "As a kinase, the function of PIM2 mainly depends on its ability to phosphorylate, and it plays a large role in cancer." (PMID 33854618, 2021). "PIM2 therefore has important roles in cancer via the phosphorylation of essential substrates and the regulation of key signaling pathways." (PMID 33854618, 2021). "HuscFvs produced by three E. coli clones infected with the HuscFv displaying phages bound also to native PIM2 from cancer cells." (PMID 34770845, 2021). "This phosphorylation of PKM2 increased cancer cell proliferation, and PIM2 promoted PKM2-dependent glycolysis while reducing mitochondrial respiration." (PMID 33854618, 2021). "Several chemical inhibitors targeting PIMs/PIM2 or their downstream signaling molecules have been developed for treatment of different cancers." (PMID 34770845, 2021). "Flow cytometric analysis revealed that the human cancer cells tested expressed high levels of PIM2, compared to subpopulations of blood cells of three healthy donors." (PMID 34770845, 2021). "Three E. coli clones transfected with the HuscFv genes derived from the rPIM2-bound phages expressed HuscFvs that bound also to native PIM2 from cancer cells." (PMID 34770845, 2021). "Development of anti-PIMs/PIM2 agents that are biocompatible to humans for long-term treatment of cancers through repeated administration is rational." (PMID 34770845, 2021). "Proviral integration site of Moloney virus-2 (PIM2) is overexpressed in multiple human cancer cells and high level is related to poor prognosis; thus, PIM2 kinase is a rational target of anti-cancer therapeutics." (PMID 34770845, 2021). "Previous studies on PIM2 indicated that it played multiple roles in regulating malignant phenotypes of cancer cells." (PMID 32641749, 2020). "Human PIM-2 is a proto-oncogene involved in regulating cancer biology, including cell survival and tumorigenesis." (PMID 32062612, 2020). "The function of PIM2 in cancer depends on its serine/threonine kinase activity, which can phosphorylate multiple substrates including p21, p27, NOTCH1, p65, BAD, AMPKα1, TSC2, PKM2, c-MYC, HK2 and HSF1 12, 14-18." (PMID 32754266, 2020). "Functionally, PIM2 regulated several aspects of TTP functions in the reprogramming of cancer cells through protein degradation and protein binding." (PMID 29570932, 2018). "PIM2 plays an important role in multiple types of cancer; it is frequently overexpressed in human cancers and promotes cancer‐cell proliferation and survival." (PMID 29570932, 2018).
cancer (continued). "In summary, our results demonstrated that PIM2 functions as a unique and key regulator of cancer development by virtue of its coordination of glycolysis, autophagy, and paclitaxel resistance through the phosphorylation of HK2." (PMID 29985480, 2018). "Although the oncogene functions of PIM2 are important for cancer cells, the mechanisms of regulation of glycolysis remain uncharacterized." (PMID 29985480, 2018). "For example, PIM2 modulates mTORC1 activity through phosphorylation of TSC2 in other cancers, while PIM1 phosphorylates PRAS40 thereby relieving its inhibitory effects on mTORC1 with a subsequent increase in mTORC1 activity." (PMID 27120806, 2016). "The PIM kinases are upregulated in the CD138+ fraction of patient bone marrow, and PIM2 was seen to be the most highly expressed of the three kinases within the cancer compartment." (PMID 27564460, 2016). "In this study, we found that both the mRNA and protein levels of PIM2 were significantly induced by hypoxia in human cancer cells." (PMID 24505470, 2014). "Serine/threonine kinase proto-oncogene PIM2 level was induced upon hypoxia in a HIF-1α-mediated manner in cancer cells." (PMID 24505470, 2014). "PIM2 is responsible for cell cycle regulation, cell proliferation and other malignant phenotypes of cancer." (PMID 24505470, 2014). "From this viewpoint, the ERKs and PIM2 signaling pathways, which play a key role in cell survival and cancer malignancy, may lead to cancer cell resistance to necroptosis by suppressing SPOP." (PMID 39540935, 2024). "Furthermore, COSMIC data analysis suggested that cancers in the large intestine have relatively high levels of PIM2 and ERK2." (PMID 39540935, 2024). "Here, we will focus on research concerning the role of PIM2 in cancer." (PMID 33854618, 2021). "According to previous reports, PIM2 promotes the progression of a diverse range of cancers." (PMID 34511042, 2021). "The effect of PIM2 on signaling pathways plays an important role in cancer regulation." (PMID 33854618, 2021). "In this review, we have outlined the many possible PIM2 pathways, and each of these may be a potential therapeutic target for treating cancer." (PMID 33854618, 2021). "Western blotting was used to measure PIM2 expression levels in cancer tissues and cells." (PMID 34511042, 2021). "It reported that PIM-2 cooperates with XIAP to mediate cancer cells apoptosis." (PMID 32062612, 2020). "PIM2 is an oncogene that regulates many signal pathways in cancer." (PMID 29570932, 2018). "PIM2 is upregulated in multiple cancer types and promotes cancer‐cell survival by unknown mechanisms." (PMID 29570932, 2018). "Under hypoxia, HIF-1α shunts glucose toward glycolysis to maintain cell survival, so we investigated whether PIM2 could augment adaptive responses to hypoxia by increasing glycolysis in cancer cells." (PMID 24505470, 2014). "Importantly, PIM2 inactivation can restore apoptosis to otherwise drug-resistant cancers and is therefore an attractive therapy to supplement current drug regimes such as GleevecTM." (PMID 19841674, 2009). "Therefore, studying the efficacy of the ERK2/PIM2-SPOP-RIPK3 signaling pathway in chemoresistance mechanisms could be pivotal for developing broader cancer treatment strategies." (PMID 39540935, 2024). "Furthermore, PIM2 may also phosphorylate PΚM2 and HΚ2 (key glycolytic enzymes) to promote glycolysis in cancer cells." (PMID 33854618, 2021). "Moreover, PIM2 plays an important role in regulating glycolysis, and promotes cancer progression." (PMID 29985480, 2018). "Therefore, as a target for cancer treatment, PIM2 knockdown might be more efficient than the drug‐induced inhibition of PIM2 kinase activity." (PMID 29570932, 2018).